CTLA4 (cytotoxic T-lymphocyte associated protein 4)
Diseases named in the same sentence as CTLA4 in open-access papers (continued):
Sharing a sentence is not in itself a finding about the gene and the disease.
tumor (continued). "Higher tumor TIDE prediction scores were associated not only with poor efficacy of immune checkpoint inhibition therapy but also with poor survival of patients treated with anti-PD1 and anti-CTLA4." (PMID 35295857, 2022). "Cytotoxic T lymphocyte-associated protein 4 (CTLA-4) belongs to the CD28 receptor family, which was identified to be activated on the exterior of conventional T cells and attenuate tumour cell proliferation by inhibiting T-cell proliferation and IL-2 secretion." (PMID 35896612, 2022). "Immune checkpoint inhibitors that block the immunosuppressive receptors such as cytotoxic T-lymphocyte-associated antigen 4 (CTLA-4) and PD-1 can reverse the dampened antitumor immune response of T cells in the tumor microenvironment and trigger anticancer properties of infiltrating T cells." (PMID 36742345, 2022). "Combination of immunotherapy, such as antibody against PD-1/PD-L1 with antibody against LAG3, TIM3, or CTLA4, could further increase tumor-infiltrating lymphocyte functions." (PMID 35892867, 2022). "The basic principle is to resist the immunosuppressive effect of the tumor microenvironment by targeting the immune checkpoint receptors—CTLA4, PD1 and their ligands (PDL1, PDL2), so as to remove the immune suppression and enhance the immune function to play an anti-tumor role." (PMID 36536343, 2022). "However, when the orders were reversed, the anti-tumor effects of anti-CTLA-4 were decreased, and CD8+ T cells underwent massive apoptosis." (PMID 36003765, 2022). "To assess whetheran adaptive immune response could be generated against KP tumours, we treatedtumour-bearing mice with a combination of anti-PD-L1 and anti-CTLA-4." (PMID 35930804, 2022). "Targeting immune checkpoint molecules such as PD-1 and CTLA-4 can reinvigorate anti-tumor immunity." (PMID 35836573, 2022). "The CTLA-4 pathway plays an important role in the early stage of immune system activation, and the PD-1 / PD-L1 pathway plays an important role in immune system tumor microenvironment and is related to tumor immune escape mechanism." (PMID 35479513, 2022). "Therefore, PD-1/PD-L1 blockers and CTLA-4 inhibitors play different roles by blocking parallel but different pathways on tumor cells." (PMID 36032103, 2022). "In some clinical trials, tumor vaccine is used with CTLA-4 blockade for TNBC treatment." (PMID 34875483, 2022). "Additionally, it is important to note that there was reduced NLRP3/caspase-1 complex activity in the transgenic tumor-bearing mice upon treatment with anti-CTLA4 in all three cohorts." (PMID 35741331, 2022). "In addition, significant increases in the number of tumor-infiltrating immune cells, specifically cytotoxic T-cells, were observed in the TTFields plus anti-PD-1/anti-CTLA-4 or anti-PD-L1 groups." (PMID 36430552, 2022). "A mouse model further found that although CTLA-4 inhibition partially restored tumor infiltration of T cells alongside consequent dexamethasone exposure, there was no significant increase in CD8 T cells, hence suggesting that early exposure to steroids led to significantly suppressed ICI response." (PMID 35267602, 2022). "However, the effective suppression of tumor growth was observed only when anti-VISTA antibodies were used in combination with anti-PD-1 antibodies or CTLA-4." (PMID 36140182, 2022). "The combination of STING agonists with ICIs (PD-1 inhibitor or CTLA-4 antibody) has presented significant synergistic anti-tumor effects in several tumor models, and the clinical efficacy of STING agonists integrated with PD-1 antibody is under investigation in patients for cancer immunotherapy." (PMID 35889509, 2022). "Accordingly, the immune checkpoint inhibitors targeted at PD-1 (nivolumab and pembrolizumab), PD-L1 (atezolizumab, avelumab and durvalumab) and CTLA-4 (ipilimumab and tremelimumab) are capable of blocking these essential routes and thereby tightening up the immune surveillance over tumor cells." (PMID 36143308, 2022).
tumor (continued). "Notably, a combination of VSV∆51-amiR-4 with anti-CTLA4 antibodies enabled profound tumour control and relapse-free rejection in 60% of the mice." (PMID 35393414, 2022). "Notably, CCL14 expression in HCC negatively correlated with PD-1, HAVCR2, and CTLA-4, suggesting its role in regulating tumor immunity." (PMID 36159990, 2022). "A previous study showed that CTLA4 is expressed not only by T cells but also by tumor cells, which indicates that the exact function of CTLA4 is unknown." (PMID 36119033, 2022). "in the microbiome of tumor-bearing mice responsive to anti-CTLA-4 therapy." (PMID 35474500, 2022). "Immunosuppressive effects of RT in the TME include an increased infiltration of regulatory T cells (Tregs), M2 tumor-associated macrophages (TAMs), and MDSCs, along with the expression of immune checkpoints molecules such as PD1/PDL1, CTLA4, and CD47 on tumor cells." (PMID 36018888, 2022). "Upon reaching the tumor, the outer domain is cleaved by membrane type-serine protease 1 (MT-SP1) present in the tumor microenvironment, leading to enhanced localization of anti-CTLA4 without causing significant treatment-associated toxicity." (PMID 35222418, 2022). "Studies have shown that the mRNA and protein expression levels of the immune checkpoint molecules PD-L1 and CTLA4 are also closely related to high TILs, an active immune response, and a “hot” immune microenvironment, which is beneficial for the tumor-targeted immune response or immunotherapy." (PMID 35928964, 2022). "Furthermore, the efficacy of anti-CTLA-4 is enhanced through B. fragilis which tends to activate Th1 cells and their cross reactivity with bacterial antigens and new tumor antigens." (PMID 35600385, 2022). "Similarly, while anti-CTLA-4 antibody partially suppressed tumor growth in both models, the combination of K3-SPG-ISV and CTLA-4 blockade showed marked tumor growth inhibition, where the synergistic effect was clear particularly in the CRC model." (PMID 35136110, 2022). "Anti-PD-L1 and a combination of anti-PD-1 and anti-CTLA4 both increase the formation of TLSs in the tumor microenvironment, resulting in reduced tumor growth, and increased T cell recruitment to the tumor, as indicated by the formation of discrete T cell and B cell zones." (PMID 35053457, 2022). "Flow cytometry analysis of subcutaneous tumours treated with anti-CTLA-4or anti-PD-1 demonstrated that only anti-CTLA-4 treatment effectively depletedFoxp3+ Tregs,resulting in an increase in the ratio of CD8+ and CD4+effector T cells to Tregs, as previously reported." (PMID 35930804, 2022). "Therefore, studies have found that the use of CTLA-4 antibody can induce the expansion of tumor-infiltrating CD 8 + T cell Th1-like CD 4 + T cell subsets." (PMID 35923703, 2022). "According to these studies, CD80-Fc may even be effective in treating anti-PD-1 or anti-CTLA-4 -resistant patients and in our study its combination with 4-1BBL-Fc enhanced immune response against tumor cells." (PMID 36480493, 2022). "According to the results of the Western blot, CTP significantly increased the levels of CD4, CD8, and IL-2, and reduced the levels of CTLA4 and PD-L1 in the tumor, and CTLA4 and PD-1 in the spleen of ApcMin/+ mice; this underscored the pivotal role of IL-2 in the immune response." (PMID 35662701, 2022). "Since tumor-expressed B7x reduced the efficacy of anti-CTLA-4 treatment, we next asked if this phenotype could be overcome by administering an anti-B7x antibody." (PMID 35523809, 2022). "Notably, therapeutic efficacy of nCHI3L1 Abs was better than that of anti-CTLA-4 antibody (α-CTLA-4) in LLC subcutaneous tumor growth model." (PMID 34987649, 2022). "A recent study showed that tumor resistance to anti-programmed cell death-1 (anti-PD-1) therapy might be related to an increase in CTLA-4+Tregs." (PMID 35965549, 2022).
tumor (continued). "A study found that TIGIT, but not the other checkpoint molecules PD-1 and CTLA-4, was linked with NK cell exhaustion in both humans and tumor-bearing mice with colon cancer." (PMID 36233088, 2022). "Some Researchers have designed a probiotic therapy that may improve the safety of tumor immunotherapy, including immunotherapy targeting PD-L1 and CTLA-4." (PMID 35844804, 2022). "This hypothesis is supported by previous studies showing that a favorable microbiota in positive responders to CTLA-4 or PD-1 blockade have lower numbers of peripheral blood and tumor Treg cells." (PMID 35677057, 2022). "Together, the results indicate that the effect of PF543 on tumor-infiltrating CTL activation and the profound association of PF543 and attenuated immunosuppressive cells indicate that PF543 likely contributes to augmented CTLA-4 mAb efficacy." (PMID 36050478, 2022). "CD274, PDCD1 and CTLA4 are vital immune checkpoints that are responsible for tumor immune escape." (PMID 35637248, 2022). "The results of PET and ex vivo biodistribution studies in immune deficient BALB/c mice grafted with syngeneic mouse tumor model (CT26), which expresses CTLA-4, indicated specific uptake of [64Cu]Cu-DOTA-anti-mouse CTLA-4 mAb when compared to the IgG control mAb." (PMID 35625811, 2022). "Notably, ZVI-NP enhanced anti-tumor immunity via transforming pro-tumor M2 macrophages into anti-tumor M1, reducing Tregs and down-regulating CTLA-4 and PD-1 in CD8 + T cells to provoke their cytolytic activity against cancer cells." (PMID 36335094, 2022). "Interestingly, the addition of propranolol further delayed tumor growth and improved the survival rate compared to anti-CTLA4 alone." (PMID 35017664, 2022). "Since STING agonists promote immune responses, co-injection of immune checkpoint inhibitors (anti-CTLA-4 and anti-PD-1) may further enhance anti-tumor effects." (PMID 35267494, 2022). "Therefore, it can be concluded that combination of CTLA-4 blockade with MUC1 mRNA nanovaccine enhances anti-tumor cytotoxic T-lymphocyte activity by reducing immunosuppressive TME and inhibiting tumor-promoting STAT3 signaling pathway." (PMID 34875483, 2022). "Nivolumab and the cytotoxic T-lymphocyte antigen-4 (CTLA-4) inhibitor ipilimumab have distinct but complementary mechanisms of action that contribute to the restoration of anti-tumour T-cell function and induction of de novo anti-tumour T-cell responses, respectively." (PMID 35322232, 2022). "In the orthotopic KPC1 model where Slc4a4 targeting per se already displayed a strong reduction in tumor growth, we could observe a trend in tumor growth reduction by adding the treatment with anti-PD-1 and anti-CTLA-4 together." (PMID 36522548, 2022). "With these immunosuppressive environments, inhibitory receptors including programmed cell death protein 1 (PD-1), cytotoxic T lymphocyte-associated protein 4 (CTLA-4), and lymphocyte activation gene (LAG-3) are upregulated in tumor cells and APCs to further inhibit the T cell effector functions." (PMID 35806328, 2022). "The immunological score could predict the anti-CTLA-4 and anti-PD-1 antibody response, which can identify determinants of tumor immunogenicity." (PMID 35547808, 2022). "Thus full activation of T cells requires binding of CD28 to CD80 and CD86, but in tumors, CTLA-4 is frequently upregulated, as a consequence of T cell exhaustion due to long time exposure to tumor cells." (PMID 35251003, 2022). "In particular, the effective timing of the administration of the anti-CTLA4 mAb, which may deplete Tregs and prevent local Treg-accumulation of the tumor, needs to be investigated in detail." (PMID 35763240, 2022). "Studies have shown that CTLA-4 not only attenuates the antitumor immune response by being expressed on tumor-infiltrating lymphocytes but also enables tumor cells to escape the immune response by being expressed on the tumor cell surface, thereby promoting tumor growth." (PMID 35531124, 2022).
tumor (continued). "In recent years, research on immune checkpoint inhibitors, such as programmed cell death protein-1/PD-L1 inhibitors and anti-cytotoxic T lymphocyte-associated antigen 4 (CTLA-4) inhibitors, has become important for identifying key roles in tumor-induced immunosuppression." (PMID 35928449, 2022). "The complex tumour immune microenvironment of the LHIC is also one of the main causes of the heterogeneity of the treatment response to immune checkpoint blockers such as PD-1 and CTLA-4 blockade in LHIC patients with the same TNM stage." (PMID 35592424, 2022). "Also, Cytotoxic T-Lymphocyte Associated Protein 4 (CTLA-4) was genetically knocked down using shRNA, which benefited CAR-T cell anti-tumor function." (PMID 36419058, 2022). "Thus, combining radiotherapy and anti-CD25/CTLA-4 monoclonal antibody resulted in decreased Tregs and enhanced anti-tumor immunity, suppressed the tumor growth, and improved the overall survival." (PMID 35585567, 2022). "Anti-CTLA-4 antibody may kill tumor-infiltrating effector Treg cells or decrease their suppressive activity." (PMID 34875483, 2022). "CTLA-4 and PDCD-1 are two critical proteins associated with tumor immune escape." (PMID 35769911, 2022). "In both preclinical models, it was observed that repression of CTLA-4 or PD-1 resulted in diminished tumor vascular density, enhanced vascular perfusion, as well as alleviated hypoxia in the tumor bed, all of which are perceived as the central features of tumor vascular normalization." (PMID 36439137, 2022). "However, the triple combination of PIC + RT + anti-CTLA-4 significantly suppressed tumor growth in this model and improved overall survival compared to RT + anti-CTLA-4 treatment." (PMID 35999216, 2022). "CTLA-4 inhibits the early activation and differentiation of T cells (usually in the lymph nodes), while PD-1 transmits inhibitory signals and regulates the effector function of T cells (mainly in the tumor)." (PMID 35296094, 2022). "Also, based on its in vitro activity to block the interaction between CTLA-4 and B7 ligand, our data suggest that the anti-tumor efficacy of half-life extended H11 would be attributed to inhibition of the interaction between CTLA-4 and its ligands." (PMID 35237846, 2022). "Additionally, we noted lower levels of PD1 and CTLA4 suggesting a possible blockade of these immune checkpoints in DCZ0415‐treated tumours that improved cytotoxicity and tumour regression." (PMID 35194944, 2022). "This demonstrates that Nivolumab and Ipilimumab synergistically promote T-cell anti-tumor activity through complementary mechanisms of action, which provides a clinical experimental basis for CTLA-4 inhibitors combined with PD-1 inhibitors in the treatment of MSI-H/dMMR mCRC." (PMID 35911673, 2022). "Therefore, immunotherapies target co-inhibitory receptors, such as CTLA-4, PD-1, and PD-L1, on tumor cells or immune cells, in order to prevent T cell dysfunction and apoptosis and enhance T cells’ ability to kill tumor cells." (PMID 35619103, 2022). "The PD-1 and CTLA-4 is now regarded as promising target in tumor treatment." (PMID 35281830, 2022). "In a therapeutic setting, iCCA-bearing rats received either DNA plus Protein vaccines or Protein vaccine alone, resulting in increased PD-L1 and CTLA-4 antibody titers, and reduced iCCA tumor burden as verified by animal positron emission tomography (PET) scans." (PMID 36341387, 2022). "GM-CSF was found to improve the anti-tumor effects of B16 melanoma tyrosinase-related protein 2 (TRP-2) peptide vaccines in combination with anti-CTLA-4 antibody by increasing the frequency of TRP-2-specific, IFN-secreting T cells in spleen and lymph nodes via DC priming and activation." (PMID 35865534, 2022). "The regulatory mechanism of surface expression of CTLA-4 is crucial for anti-tumor immunity." (PMID 36528587, 2022).
tumor (continued). "Therefore, by inhibiting PD-1 or CTLA4 checkpoints or simultaneously inhibiting PD-1 or CTLA4 checkpoints, tumor-specific T cells can be expanded and stimulated to perform anti-tumor functions." (PMID 35911673, 2022). "Similar effects have been observed in solid tumor trials where anti–CTLA-4 has been combined with anti–PD-1, resulting in a widened immune repertoire and reactivation of the putative tumor-reactive, terminally differentiated memory T cells with clinical benefit." (PMID 36047494, 2022). "For example, differences in the immune checkpoint inhibitors evaluated (e.g., anti–PD-1 monotherapy and combination of anti–PD-1 and anti–CTLA-4 therapy), particularly when comparing studies across tumor types, complicate the ability to generalize the results of these studies." (PMID 35565428, 2022). "This study suggested that this tumour infiltration with CD4+ T cells occurred via CTLA-4 expressed on regulatory T cells interacting with CD80-expressing dendritic cells present in peritumoral lymph nodes, thus demonstrating a role for CTLA-4/CD80 interaction in T-cell exclusion." (PMID 35626020, 2022). "Importantly, combination of RBMS1 depletion with CTLA4 immune checkpoint blockade or CAR-T treatment enhanced anti-tumor T-cell immunity both in vitro and in vivo." (PMID 35538152, 2022). "Accordingly, we hypothesized that the expression of CTLA-4 on DCs inhibits the T cell-mediated anti-tumoral responses generated following the presentation of tumor antigens by DCs to T lymphocytes." (PMID 35979362, 2022). "In this study, CTLA4 was found to be overexpressed in the tumor group than in the normal group." (PMID 35872842, 2022). "Anti-CTLA-4 antibodies have pioneered the field of tumour immunotherapy." (PMID 36119113, 2022). "The checkpoint blockade by anti-CTLA4 antibody or anti-PD1 antibody showed limited clinical efficacy and it is already known that the over-expression of PD-L1 in MA tumor cells is associated with CD8+ T cells malfunction and reduction in the anti-tumoral response." (PMID 36142615, 2022). "High tumour uptake correlated with response to CTLA-4 immunotherapy in xenograft mouse model." (PMID 36297474, 2022). "Moreover, co-administration of HDACIs and anti-CTLA4 (cytotoxic T-lymphocyte antigen 4) antibodies seems to act synergistically for the therapeutic effect, enhancing T-cell infiltration within the tumor and the anti-tumor immune response." (PMID 35334808, 2022). "Anti-CTLA4 therapy promotes tumor-specific CD8+ T cell proliferation in secondary lymphoid organs." (PMID 36428613, 2022). "The use of anti-CTLA-4 (IgG2a isotype) in two murine subcutaneous CRC tumor models demonstrated successful reduction of TI-Treg cells together with the expansion of CD8+ Teff cells promoting anti-tumor activity." (PMID 35874729, 2022). "On the other hand, the blockade of CTLA-4 might be more beneficial to treat MC-C than LMM3 growing tumors by enhancing an ongoing anti-tumor immune response." (PMID 35922755, 2022). "Similar tendencies were observed in a study conducted on 53 patients with NSCLC, where intratumoral Treg cells presented higher levels of immunosuppressive molecules, such as LAG-3, CTLA-4 and PD-1 than Tregs from tumor-adjacent tissues or peripheral blood Treg cells." (PMID 36077354, 2022). "In addition to upregulation of CTLA-4 and PD-1 on tumor-infiltrated T cells, in many tumors, the CD28 ligands CD80 and CD86 are poorly expressed both on tumor cells and tumor-associated myeloid cells." (PMID 35379805, 2022). "Similarly to CTLA-4, PD-1 regulates T cell activation by binding to PD-L1 and PD-L2 expressed in infiltrating inflammatory cells and tumor cells." (PMID 35251003, 2022). "In addition, more meticulous tumor biological stratification has led to successfully durable responses to PD1 and CTLA4 inhibitors in some patients, such as tumor mutation burden (TMB) and tumor environment (TME)." (PMID 35844556, 2022).